MFAP3L (microfibril associated protein 3 like)
Description:
May participate in the nuclear signaling of EGFR and MAPK1/ERK2. May a have a role in metastasis.
Synonyms: KIAA0626; NYD-sp9; LOC101928198
Tractability: Antibody: UniProt places it where antibodies can reach, with high confidence; its Gene Ontology location is reachable by antibodies, with high confidence; UniProt predicts a signal peptide or a membrane-spanning region. PROTAC: ubiquitination databases record sites on it.
Gene: Protein-coding gene on chromosome 4 (169,986,597 to 170,033,031, reverse strand). Ensembl gene ENSG00000198948.
Subcellular location: Cell membrane; Nucleus; Cytoplasm
Subcellular location (Human Protein Atlas): Nucleoplasm; Cell Junctions
Gene Ontology:
Molecular function: protein binding
Cellular component: cell junction; cytoplasm; nucleoplasm; nucleus; plasma membrane; neuron projection
Genetic constraint (gnomAD): Loss-of-function variants: 9 observed, 27.22 expected, observed/expected ratio (o/e) 0.33, 90% interval 0.2 to 0.58. The upper end of that interval is the gene's LOEUF score, 0.58, which puts it in group 2 of 6, group 1 being the genes least tolerant of losing a copy. Missense variants: 409 observed, 556.11 expected, observed/expected ratio (o/e) 0.74, 90% interval 0.68 to 0.8. Synonymous variants: 219 observed, 225.13 expected, observed/expected ratio (o/e) 0.97, 90% interval 0.87 to 1.09.
Homologues: Orthologues: chimpanzee MFAP3L (99% identical), macaque MFAP3L (99% identical), guinea pig MFAP3L (93% identical), dog MFAP3L (92% identical), rabbit MFAP3L (92% identical), rat Mfap3l (90% identical), mouse Mfap3l (90% identical), pig MFAP3L (81% identical), tropical clawed frog mfap3l (60% identical), zebrafish mfap3l (54% identical). Paralogues in human: MFAP3 (44% identical).
Diseases named in the same sentence as MFAP3L in open-access papers:
MFAP3L is named in the same sentence as 7 diseases in open-access papers, as found by Europe PMC text mining. Sharing a sentence is not in itself a finding about the gene and the disease. The quoted sentences say what the papers report.
colon cancer (1 paper, 2025). "Overexpression of MFAP3L initiates the ERK signaling cascade, promoting the expression of ERK regulatory genes and enhancing metastasis and invasion in colon cancer cells." (PMID 40598621, 2025).
colorectal cancer (1 paper, 2017). A primary or metastatic malignant neoplasm that affects the colon or rectum. "For example, activation of MFAP3L can promote colorectal cancer cell invasion and metastasis." (PMID 29312626, 2017).
lung adenocarcinoma (1 paper, 2025). A carcinoma that arises from the lung and is characterized by the presence of malignant glandular epithelial cells. "In this study, four key biomarkers closely related to mesenchymal stem cell proliferation/differentiation (MSCPD) were identified in lung adenocarcinoma (LUAD), namely MS4A2, IGSF10, NTRK3, and MFAP3L." (PMID 40598621, 2025).
retinal disease (1 paper, 2017). "According the paper, among these DEGs, PTPRG, CSPG5 and NAV3 are at loci associated with retinal disease; MFAP3L, CSPG5 and PAK1IP1 locate in the regions carrying SNP's significantly associated with AMD." (PMID 28924976, 2017).
tumor (3 papers, 2017 to 2025). "Crucially, whether these genes influence tumor development through established pathways—FcεRI signaling (MS4A2), Integrin-β1/FAK (IGSF10), or ERK transduction (MFAP3L)—requires further validation, as does their relationship with MSC activity." (PMID 40598621, 2025). "Notably, genes such as NRG1, SAMD13, MFAP3L, SALL1, ZNF704, SEMA5A, and HLA-DQB1 were identified as having altered expression patterns, potentially reflecting the diverse roles of FGFRS in tumor biology." (PMID 39676867, 2024).
MFAP3L also shares sentences with these, for which no sentence is quoted: cancer (1 paper); non-small cell lung carcinoma (1).